AVP (arginine vasopressin)
Diseases named in the same sentence as AVP in open-access papers (continued):
Sharing a sentence is not in itself a finding about the gene and the disease.
diabetes insipidus (continued). "In central diabetes insipidus (CDI) mutations in the gene encoding AVP lead to insufficient amounts of AVP released from the pituitary gland." (PMID 26903868, 2016). "Central Diabetes Insipidus (DI) in newborns and infants is due to the deficiency of arginine vasopressin (AVP) from the posterior pituitary and is associated with septo-optic dysplasia and other midline malformations." (PMID 25002871, 2014). "Diabetes insipidus (DI) is either due to deficient secretion of arginine vasopressin (AVP), also known as antidiuretic hormone (ADH) by the pituitary gland (central diabetes insipidus) or due to renal tubular unresponsiveness to AVP (nephrogenic DI)." (PMID 24977135, 2013). "Diabetes Insipidus (DI) is either due to deficient secretion of arginine vasopressin (central) or to tubular unresponsiveness (nephrogenic)." (PMID 24977135, 2013). "Both father and daughter were found to have the pathogenic mutation c.242T>C (p.Leu81Pro) in exon 2 of the AVP gene consistent with a diagnosis of familial diabetes insipidus." (PMID 24616780, 2013). "At this point, administering desmopressin will not further increase the urine osmolality only if we have deficient endogenous arginine vasopressin as in central diabetes insipidus." (PMID 24977135, 2013). "Autophagy deficiency in mouse AVP neurons leads to the late‐onset of diabetes insipidus." (PMID 40051383, 2025). "Thus, either autophagy or ERAD deficiency in AVP neurons will result in impairment of misfolded proAVP clearance and diabetes insipidus." (PMID 40051383, 2025). "The 3 main causes, recently renamed to arginine vasopressin deficiency (AVP-D, formerly central diabetes insipidus), arginine vasopressin resistance (AVP-R, formerly nephrogenic diabetes insipidus), and primary polydipsia (PP) require accurate diagnosis, as management differs for each." (PMID 39148427, 2025). "AVP-D, formerly called central diabetes insipidus, is due to a deficiency of the AVP hormone." (PMID 40951256, 2025). "Finally, we believe the names of medical disorders optimally should reflect the underlying pathophysiology, which in the case of diabetes insipidus is now well known to be deficient secretion and/or end-organ effects of the hormone arginine vasopressin (AVP)." (PMID 36183693, 2023). "On the example of this clinical case, we will try to highlight the differential diagnostic criteria for psychogenic polydipsia in comparison with the true deficiency of arginine vasopressin (AVP) or central diabetes insipidus (CDI), which can be applied in real clinical practice." (PMID 38796762, 2023). "Finally, we believe the names of medical disorders should, ideally, reflect the underlying pathophysiology, which in the case of diabetes insipidus is now well known to be deficient secretion and/or end-organ effects of the hormone AVP." (PMID 36228658, 2022). "Cranial diabetes insipidus is a condition caused by reduced AVP production in the pituitary." (PMID 34787082, 2021). "Alternatively, hypoarousal could be a side effect of diabetes insipidus – polydipsia and polyuria seen in Hom rats due to loss of AVP facilitation of water reabsorption in the kidney." (PMID 31160697, 2019). "Notably, individuals with familial central diabetes insipidus, polydipsia and polyuria due to a mutation in the AVP gene, exhibit deficits in sustained attention." (PMID 31160697, 2019). "Once overexpressed, AVP may contribute to hyper-anxiety and depression-like behaviors, whereas AVP deficits may, in addition to diabetes insipidus, cause signs of hypo-anxiety and disturbed rhythmicity." (PMID 24318124, 2014). "Aberrant transcription products might be retained in the endoplasmic reticulum or could act as neurotoxic agents, as already demonstrated for pro-dynorphin in ataxia or arginine-vasopressin variants in diabetes insipidus." (PMID 23936060, 2013).
diabetes insipidus (continued). "Furthermore, we demonstrated that combined inhibition of ERAD and autophagy in AVP neurons led to even more severe accumulation of misfolded proAVP in vitro, and led to even most severe diabetes insipidus phenotype in vivo, compared with deficiency of either pathway." (PMID 40051383, 2025). "Thus, copeptin may serve as a bona fide biomarker of AVP release based on large studies and may be useful to distinguish in some circumstances among different causes of diabetes insipidus." (PMID 28795329, 2017). "Arginine vasopressin (AVP) disorders (previously called diabetes insipidus) lead to excessive urination due to reduced antidiuretic hormone (ADH) secretion or kidney resistance to ADH." (PMID 40351988, 2025). "Diabetes insipidus is characterized by the excretion of a large volume of hypotonic urine due to the impaired production or action of the hormone arginine vasopressin (AVP)." (PMID 40217758, 2025). "Diabetes insipidus is classified into central diabetes insipidus when the defect involves impaired production and the secretion of AVP or nephrogenic diabetes insipidus when the kidneys are resistant to the action of AVP." (PMID 40217758, 2025). "Traumatic lesions affecting AVP neurons result in decreased AVP secretion, leading to diabetes insipidus characterized by polydipsia and polyuria." (PMID 39941427, 2025). "The evaluation of a patient with hypotonic polyuria-polydipsia syndrome (such as diabetes insipidus) has traditionally relied on a water deprivation test with an arginine vasopressin challenge." (PMID 40123924, 2025). "Mice deleted of Wnk1 in the CVOs exhibit impaired hypertonicity‐induced AVP release and phenotypes of central diabetes insipidus." (PMID 41246868, 2025). "Since these tumors can compromise the production and release of AVP, a characteristic symptom of their presence is the appearance of central diabetes insipidus, characterized by polyuria and polydipsia." (PMID 40648926, 2025). "One of the most recognized disorders involving AVP and V2R is diabetes insipidus, and the measurement of blood AVP levels is essential for diagnosing the disease." (PMID 38658606, 2024). "Since QPC deletion is restricted to kidney CD cells, it is unlikely that abnormal central AVP secretion (i.e., central diabetes insipidus) or primary polydipsia are contributing to the urinary concentration defect observed in HoxB7-Qpc–/– mutants." (PMID 39361429, 2024). "Plasma AVP is a valuable biomarker for the diagnosis of central diabetes insipidus (CDI) and is commonly measured using radioimmunoassay (RIA)." (PMID 38658606, 2024). "In the mid-20th century, arginine vasopressin was synthesized and identified as the antidiuretic hormone, and the distinct central and nephrogenic etiologies of diabetes insipidus were recognized and characterized." (PMID 36183693, 2023). "Administration of desmopressin (dDAVP), a potent and selective V2R agonist peptide, helps to differentiate between central diabetes insipidus (impaired AVP secretion) and nephrogenic diabetes insipidus." (PMID 37293495, 2023). "In contrast to Central Diabetes Insipidus which is caused by reduced secretion of AVP from the pituitary gland, NDI is caused by a resistance to AVP in the distal nephron." (PMID 37674034, 2023). "In the mid-20th century, arginine vasopressin (AVP) was synthesized and identified as the antidiuretic hormone, and the distinct central and nephrogenic etiologies of diabetes insipidus were recognized and characterized." (PMID 36228658, 2022). "It is either related to a deficit in AVP secretion called central diabetes insipidus that can be treated by AVP analogs or to a peripheral defect in AVP response called nephrogenic diabetes insipidus." (PMID 35678906, 2022). "Central diabetes insipidus (CDI) is a heterogeneous condition characterized by polyuria (urine output >2 L/m2/24 hour) and polydipsia due to a deficiency of the hormone arginine vasopressin (AVP)." (PMID 35311034, 2022).
diabetes insipidus (continued). "DI: diabetes insipidus; ADH: antidiuretic hormone; AVP: arginine vasopressin; AQP2: aquaporin-2 receptors." (PMID 33786230, 2021). "Mutations in the AVP, V2, and AQP2 genes cause forms of diabetes insipidus that have been extensively reviewed elsewhere." (PMID 33477721, 2021). "Previously, it was demonstrated that NIL induced an immediate but transient increase in water intake and urine output (diabetes insipidus) for 2-4 weeks and a permanent drop in AVP serum levels." (PMID 34926704, 2021). "Impairment of the posterior pituitary clinically presents as diabetes insipidus, which is characterized by hypotonic polyuria due to attenuated arginine vasopressin- (AVP) secretion." (PMID 32993515, 2020). "Central diabetes insipidus (CDI) is characterized by polyuria and polydipsia and caused by deficiency of arginine vasopressin (AVP), an antidiuretic hormone which acts on V2 receptors in the kidney to promote reabsorption of free water." (PMID 31049061, 2019). "p.H80Y mutation will cause inappropriate folding of the protein compromising water homeostasis via AVPR2 and AVP and leading to diabetes insipidus." (PMID 29991464, 2018). "Regarding arginine vasopressin (AVP), three disorders are listed as endocrine diseases, namely, central and nephrogenic diabetes insipidus, and syndrome of inappropriate secretion of antidiuretic hormone (SIADH)." (PMID 29088071, 2017). "Copeptin serves as a bona fide biomarker of AVP release based on large studies and is very useful in the diagnosis of diabetes insipidus." (PMID 26578365, 2016). "Central diabetes insipidus (CDI) results from deficiency synthesis, release of arginine vasopressin (AVP), or both." (PMID 27118970, 2016). "Demeclocycline, an antibiotic, which belongs to the tetracycline family, counteracts the effects of AVP by inducing a partial, reversible nephrogenic diabetes insipidus." (PMID 26553121, 2015). "Arginine vasopressin dosages have been performed at baseline and were high in patients with nephrogenic diabetes insipidus and low in patients affected by central diabetes insipidus (median: 12.3 and 2.0 pg/mL, respectively, P = 0.03)." (PMID 26620256, 2015). "In our experience, this can be particularly difficult in the early phase of cranial diabetes insipidus (CDI) when AVP secretion is declining." (PMID 24616780, 2013). "A decrease or increase in urinary AQP2 levels was shown to correspond with diminished or exaggerated levels of AVP, as seen in central diabetes insipidus or SIADH, respectively." (PMID 22325688, 2012). "Neurogenic diabetes insipidus is defined as a decreased secretion of arginine vasopressin (AVP) leading to a high urine output of greater than 30 mL/kg per 24 hours." (PMID 20673320, 2010). "Plasma AVP concentration also exhibited a triphasic pattern in accord with the pattern of diabetes insipidus." (PMID 18578860, 2008). "Following neurohypophysectomy, rats exhibit a pronounced diabetes insipidus and dramatically decreased urinary levels of AVP." (PMID 18578860, 2008). "In one word, there was tight time correlation between the occurrence of diabetes insipidus, plasma AVP concentration and the degeneration of AVP neurons after hypophysectomy." (PMID 18578860, 2008). "From 10 d plasma AVP concentration decreased and diabetes insipidus occurred again because of the significant degeneration of AVP neurons." (PMID 18578860, 2008). "Unexpectedly, we demonstrated that ATG7AVP mice developed late‐onset diabetes insipidus under normal conditions, but showed overall reduction in proAVP synthesis with comparable maturation efficiency and increased ER stress in AVP neurons, before the onset of diabetes insipidus." (PMID 40051383, 2025). "TSS for PitNETs carries a risk of posterior pituitary lobe injury, which may precipitate diabetes insipidus (DI) through disruption of arginine vasopressin (AVP) secretion." (PMID 41180200, 2025).
diabetes insipidus (continued). "This indicates that patients with diabetes insipidus may be more prone to fluctuations in urine output in the setting of SGLT2 inhibitor use due to impaired endogenous AVP production or action." (PMID 40217758, 2025). "Clinically, anemia is more prevalent in patients with central diabetes insipidus, in whom hypothalamic AVP synthesis is deficient, although direct evidence linking AVP to renal anemia in PD is lacking." (PMID 41157262, 2025). "Specifically, lower AVP levels result in increased urine excretion, and in cases of complete central diabetes insipidus, urine excretion rates may reach up to 1000 milliliters per hour." (PMID 39941427, 2025). "Their slow growth, unlike metastases, makes degeneration of more than 80–90% of the AVP-secreting neurons in the hypothalamic supraoptic and paraventricular nuclei, a necessary threshold for developing diabetes insipidus before the tumor is clinically detected by its mass effects, unlikely." (PMID 40648926, 2025). "Central diabetes insipidus (CDI), is a possible consequence of pituitary manipulation and is caused by a transient or permanent deficiency in the secretion of arginine vasopressin (AVP) by the neurohypophysis and in most cases, resolves within 10 days." (PMID 38847919, 2024). "Low serum arginine vasopressin levels confirmed the diagnosis of central diabetes insipidus." (PMID 39171059, 2024). "Animals with knockdown of Creb3l1 in the SON displayed classic signs of diabetes insipidus with increased fluid intake and the production of higher volumes of diluted urine (polyuria) compared to controls, likely due to insufficient release of AVP and OXT." (PMID 35803572, 2022). "Conversely, hypernatremia is the common finding of an insufficient AVP secretion, as observed in central diabetes insipidus (CDI), or an insufficient AVP action despite increased release, in case of AVP receptor resistance (nephrogenic diabetes insipidus, NDI)." (PMID 32809080, 2021). "Pituitary surgery often impairs AVP release and results in central diabetes insipidus (CDI)." (PMID 34446748, 2021). "Molecular analysis disclosed no other variants of clinical significance in AVP or central diabetes insipidus (CDI) or CNDI related genes." (PMID 34956990, 2021). "Thus, the molecular strength and precision of the diuretic renal response to AVP suppression is powerful and allows for urinary excretion rates approximating 1 L/h, as seen in patients with diabetes insipidus and compulsive water drinkers." (PMID 31284689, 2019). "At the most extreme range of overhydration, compulsive water drinking has been recognized in emotionally disturbed individuals without neurogenic (i.e., inability of secrete AVP from the posterior pituitary) or nephrogenic (i.e., kidneys resistant to AVP stimulation) diabetes insipidus." (PMID 31284689, 2019). "However, 16γzf threads strikingly resemble those formed by diabetes insipidus-inducing mutants of the antidiuretic hormone arginine vasopressin precursor." (PMID 30085182, 2018). "In conclusion, we showed in human study that masked diabetes insipidus could be mediated by AVP-independent mechanisms." (PMID 21811505, 2011). "Diabetes insipidus is a kind of pathologic state resulting from decreased ability of the kidney to concentrate urine because of the decreased secretion of AVP from the posterior pituitary gland or resistance to the action of AVP." (PMID 18578860, 2008). "Central diabetes insipidus (CDI) is caused by the destruction or degeneration of neurons originating in the supraoptic and paraventricular nuclei of the hypothalamus, leading to a deficiency in the secretion of arginine vasopressin (AVP), polyuria, and polydipsia." (PMID 37697216, 2023).
diabetes insipidus (continued). "Diabetes insipidus (DI) is a condition characterized by the excretion of large volumes of hypotonic urine either due to the deficiency of the antidiuretic hormone (ADH), also known as arginine vasopressin, or to resistance to the action of this hormone on its receptors in the kidney." (PMID 35311088, 2022). "Thus, urea levels might reflect AVP action in the nephrons and may differentiate patients with diabetes insipidus from dehydrated states." (PMID 29422070, 2018). "Central diabetes insipidus (CDI) results from reduced synthesis and secretion of arginine vasopressin (AVP) due to various etiologies, leading to markedly decreased plasma AVP levels." (PMID 41211065, 2025). "The most prevalent type is central diabetes insipidus (CDI), which stems from either an acquired or genetic issue in the neurohypophysis, resulting in a decrease in arginine vasopressin (AVP) production and release." (PMID 39474227, 2024). "Thus, it may be hypothesized that in these patients, the AHAs were directed towards hypothalamic-releasing hormone-secreting cells rather than to AVP-secreting cells, thus causing the secondary impairment of pituitary secretions rather than diabetes insipidus." (PMID 34439190, 2021). "Central diabetes insipidus (CDI) is a polydipsia–polyuria syndrome due to the altered synthesis and secretion of AVP." (PMID 34446748, 2021). "Further, mice with Sel1L ablation in arginine-vasopressin (AVP) neurons progressively develop polyuria and polydipsia — characteristics of diabetes insipidus, due to a maturation defect of AVP precursor, proAVP in the ER." (PMID 29457782, 2018). "Diabetes insipidus is defined as the passage of large volumes (> 3 L/24 h or 2 L/m2/24 h) of dilute urine with reduced urine osmolality (< 300 mOsm/kg) and is caused by reduced or absent secretion of pituitary antidiuretic hormone arginine vasopressin or by a poor kidney response to the hormone." (PMID 29996815, 2018). "Most central diabetes insipidus (CDI) cases occur after the destruction of vasopressinergic neurons by TBIs, neoplasms, neurosurgical procedures, or autoimmune inflammation involving AVP-secreting neurons." (PMID 39941427, 2025). "Drug-induced diabetes insipidus occurs following the administration of medications such as lithium; however, it typically results from increased resistance to AVP and does not show responsiveness to AVP, as observed in this case." (PMID 39176369, 2024). "This impairment leads to disrupted secretion of arginine vasopressin (AVP) and subsequent central diabetes insipidus, resulting in electrolyte imbalances, osmotic fluctuations, disturbance of the internal environment, and ultimately influencing mortality rates in experimental animals." (PMID 37780696, 2023). "When the AVP pathway does not function correctly, it leads to inadequate urine concentration (hypotonic urine), which is defined as diabetes insipidus (DI)." (PMID 35678906, 2022). "A return to regulated drinking (osmotically-driven thirst stimulation) and concomitant AVP exposure will restore AQP2 expression within collecting duct epithelium by 3–5 days and reverse the physiologic nephrogenic diabetes insipidus induced by chronic water loading in both mice and men." (PMID 31284689, 2019). "We further show that 3) this viral rescue of PVN magnocellular AVP ameliorates the diabetes insipidus of Hom rats, but 4) does not reverse the decrease in behavioral arousal of Hom rats." (PMID 31160697, 2019). "First, central diabetes insipidus (CDI) is caused by central defects, in which no or an insufficient amount of functional arginine vasopressin (AVP) is released from the pituitary." (PMID 22474537, 2012). "Damage to this region, such as from TBIs, may not lead to diabetes insipidus if the AVP-producing cell bodies in the hypothalamus remain intact since AVP can be released from higher hypothalamic areas." (PMID 39941427, 2025).
diabetes insipidus (continued). "The lack of AVP results in diabetes insipidus, which means that no other hormone can replace AVP." (PMID 35328489, 2022). "In contrast, UAQP2 was depressed in central diabetes insipidus, where AVP secretion is absent." (PMID 29088071, 2017).